LAMP3 (lysosome associated membrane protein 3)
Diseases named in the same sentence as LAMP3 in open-access papers (continued):
Sharing a sentence is not in itself a finding about the gene and the disease.
tumor (continued). "LAMP3 protein expression was mainly detected in tumor epithelial cells, only in rare occasions (<5 cases) it was also detected in tumor infiltrating lymphocyte." (PMID 25362357, 2014). "Future studies are needed to resolve discrepancies between DC and tumor epithelial cell LAMP3 expression in cancer tissues." (PMID 25362357, 2014). "Notably, LAMP3 has also been shown to promote the recruitment of Tregs and the differentiation of tolerogenic dendritic cells, both of which suppress anti‐tumour immunity." (PMID 41362116, 2025). "In hypopharyngeal squamous cell carcinoma (HPSCC), scRNA-seq analysis revealed a collaborative interplay between TAMs and LAMP3+ DCs, leading to the establishment of an immunosuppressive milieu that facilitates tumor progression by recruiting regulatory T cells while inhibiting CD8+ T-cell function." (PMID 40850976, 2025). "Central to this resistance is an immunosuppressive myeloid ecosystem—dominated by SPP1high tumor-associated macrophages, neutrophils/PMN-MDSCs, and LAMP3+ mregDCs—that enforces chemokine-driven exclusion, attenuates antigen presentation, and sustains metabolite-mediated T-cell suppression." (PMID 41567197, 2025). "Our analyses showed that LAMP3 expression is high in most tumours and low in LUAD, LUSC and PRAD." (PMID 38146591, 2024). "LAMP3 induces and promotes the migration and invasion of tumor cells." (PMID 39429383, 2024). "LAMP3 has yet to have significance in some cancers, and there are also unknown mechanisms that regulate malignant progression of tumours where LAMP3 has been identified." (PMID 38146591, 2024). "It was suggested that LAMP3 expression and immune infiltration were correlated, but various tumour types exhibited differences and it may have a positive promoting effect on patient survival by affecting immune infiltration in TME." (PMID 38146591, 2024). "Furthermore, we identified four distinct subsets of dendritic cells (DCs), including LAMP3+DCs, which have been previously reported as tumor-specific and were found to be more enriched in tumor samples in our dataset." (PMID 38311726, 2024). "Pan-cancer analysis showed that LAMP3 exhibits profound investigational significance in a wide range of cancers, with differential expression in up to 16 cancers, including upregulated expression in 12 tumour types." (PMID 38217544, 2024). "In addition, in most tumours with high LAMP3 expression, the expression of LAMP3 was positively correlated with the copy number." (PMID 38146591, 2024). "A hypoxic tumor microenvironment may lead to high expression of LAMP3 via an unfolded protein response." (PMID 39429383, 2024). "The expression profile of LAMP3 tended to be more upregulated with increasing tumour staging grade." (PMID 38217544, 2024). "This may partly explain the inability of tumour tissues with high LAMP3 expression to arrest the progression of tumour progression despite having highly infiltrated B cells and T cells." (PMID 38217544, 2024). "At last, we analysed the expression of LAMP3 and response to immunotherapy in tumours." (PMID 38146591, 2024). "This may facilitate comprehension of the significance and potential role of LAMP3 in different tumours." (PMID 38146591, 2024). "It has been shown that LAMP3 overexpression is relevant to unfavourable prognosis in various cancer patients, and LAMP3 may have significance in tumour metastasis and treatment resistance, suggesting that LAMP3 may serve as a molecular marker." (PMID 38146591, 2024). "Then, to test our hypothesis, we analysed the correlation between LAMP3 expression and the prognosis of various tumours." (PMID 38146591, 2024). "Additionally, tumor tissues had a higher proportion of LAMP3+ DCs than adjacent tissues (P < 0.05, Student’s t-test)." (PMID 37853464, 2023). "Furthermore, LAMP3+ DC infiltration level in tumor tissues was positively correlated with Treg cells (R = 0.64, P = 0.03)." (PMID 37853464, 2023).
tumor (continued). "Interestingly, the CXCL9+CD1C+ DCs cluster predominated over other clusters in the tumor tissue and was more likely to differentiate into LAMP3+ DCs, thus enhancing the immunosuppressive effect." (PMID 37187731, 2023). "Currently, research on the interaction between LAMP3+ DCs and T cells is mainly focused on the tumor field, which might provide a basis for the understanding that LAMP3 participates in T cell activation and immune regulation during HBV infection." (PMID 37006307, 2023). "Besides, both CXCL10 and LAMP3 expression in the tumor tissues indicated favorable OS in the training cohort (p = 0.006, p = 0.001, respectively) and validation I cohort (p = 0.029, p = 0.005, respectively)." (PMID 37082269, 2023). "Moreover, LAMP3 is overexpressed in various tumors and is related to a poor prognosis and tumor metastasis." (PMID 37006307, 2023). "Similarly, tumour‐infiltrating LAMP3+DCs were commonly prevalent in the peritumoural region and accompanied by CD8+ T cells, and high levels of these DCs were highly correlated with a good prognosis among patients with ESCC." (PMID 36808888, 2023). "We hypothesized that the presence of cDCs in ascites might serve as a potential source of LAMP3+ DCs in tumor tissues as we found in T cells, which require additional in vivo lineage-tracing validation." (PMID 37488416, 2023). "Within the TME, cDCs have been shown to acquire a common gene program characterized by the expression of immunoregulatory genes (e.g., CD274/PD-L1, PDCD1LG2/PD-L2 and CD200), LAMP3 and CCR7, thus informing the naming of these tumor-specific cells mregDCs or LAMP3+CCR7+ cDCs." (PMID 36949244, 2023). "In addition to conferring direct antitumour effects, mregDCs (LAMP3+ DCs) are an essential component of TLSs in human tumours." (PMID 36808888, 2023). "Peripheral DCs infiltrate into the tumor and then differentiate into LAMP3+ DCs." (PMID 35632758, 2022). "Similarly, greater downregulation of tumor promotion proteins such as CCL17, CD70, and LAMP3 during dual therapy suggests that dual therapy further augments tumor suppression." (PMID 36572780, 2022). "Recently, a novel tumor-infiltrating DC that highly expresses CCL19/LAMP3/CCR7 was identified." (PMID 36505406, 2022). "However, cDC1s and cDC2s can also differentiate into a subset of regulatory DCs (LAMP3+ DCs) to hamper anti-tumor immunity." (PMID 36505406, 2022). "We observed multiple clusters of myeloid cells in NPC tumours, among which DC_C3_LAMP3 could be considered as a group of regulatory and tolerogenic DC, showing high expression of the migration (CCR7) and maturation (LAMP3) related genes." (PMID 33531485, 2021). "Besides, the cDC3_LAMP3 cells that highly expressed LAMP3, IDO1, and CCL21 associated with high maturation and migration ability were also considered as tumor-promoting immune cells." (PMID 35087839, 2021). "Importantly, the amount of intratumor mature DCs expressing lysosome-associated membrane glycoprotein 3 (LAMP3), is closely associated with tumor-infiltrated CD8+ T cell numbers, which predict favorable prognosis in patients with ESCC." (PMID 33995371, 2021). "Developmental trajectory has revealed that LAMP3+ DCs might be differentiated from immature monocytes during tumor initiation so that NPC cells can escape from initial antigen recognition and immune attack." (PMID 34568077, 2021). "Since blocking of CCR4 could significantly reduce Tregs recruited in the tumor stage in a canine model, LAMP3+ DCs may also be a potential target for immune therapy." (PMID 33033240, 2020). "It is therefore reasonable to hypothesize that P. bivia (and possibly anaerobes) attracted by hypoxic environment, infiltrates the tumor and induces a pro-inflammatory gene expression program via up-regulation of LAMP3." (PMID 30294508, 2018).
tumor (continued). "LAMP3 is also reported to induce and promote migration and invasion of tumor cells." (PMID 28607528, 2017). "Indeed, LAMP3+ DCs have been identified in tumour-dLNs, where they may activate tumour antigen-specific T cells." (PMID 38267413, 2024). "Therefore, LAMP3 may interact with immune cells in many tumours and its expression was widely related to multiple immune factors and immune cell invasion of tumours." (PMID 38146591, 2024). "Additionally, we observed that tumor-infiltrating LAMP3+ dendritic cells may inhibit CD8+ T cells or attract regulatory T cells to the tumor area." (PMID 38552055, 2024). "In addition, LAMP3 has a negative association with tumour purity in all three types of tumours, and it has a positive association with the infiltration levels of 6 types of immune cells in all three types of tumours." (PMID 38146591, 2024). "Additionally, LAMP3+ DCs in tumor tissues showed higher levels of CD274 compared to those in normal tissues, suggesting that LAMP3+ DCs infiltrating the tumor region could directly inhibit CD8+ T cells or attract Tregs to the tumor area." (PMID 38552055, 2024). "In HCC, the proportion of LAMP3 + DCs that originated from cDC1 or cDC2 and are correlated with the malfunction of T lymphocytes is higher in tumor tissues than that in adjacent non-tumor tissues, and the fraction of pDCs in relapsed tumor samples is larger than that in primary tumor samples." (PMID 36773210, 2023). "Consequently, deciphering the heterogeneity of LAMP3+ DCs and devising strategies to target them may provide new avenues for tumor therapy." (PMID 38012715, 2023). "Therefore, we propose that intra-tumor microbiota may contribute to cervical carcinogenesis through the induction of immune response drivers, including the well-known cancer gene LAMP3." (PMID 30294508, 2018). "Our findings revealed a higher abundance of TLSs in tumor tissue with a low abundance of LAMP3+ IRF8 + DCs compared to tumor tissue with a high abundance of LAMP3+ IRF8 + DCs." (PMID 41190765, 2026). "In summary, these data demonstrate that TYK2 is predominantly expressed in human LAMP3+ CCR7+ cDCs that are enriched in CRLM and predicted to activate T cells in tumor-draining lymph nodes." (PMID 40991399, 2026). "Myeloid cells were subclustered into monocyte, Tumor-associated macrophage (TAM) including SPP1+ TAM, C1Qs+TAM, HSPs+ TAM, ACP5+ TAM, and CCL5+ TAM, classical dendritic cell (cDC) encompassing cDC, CD1A+ DC, LAMP3+ DC and PCLAF+ DC, plasmacytoid DC (pDC) as well as unknown subpopulations." (PMID 40904511, 2025). "LAMP3+DCs also show strong interaction with ERFs through COL1A2-CD44, which supports our theory that ERFs facilitate the tissue retention of tumor-promoting immune cells." (PMID 40755770, 2025). "The violin plots demonstrate that genes including CTNV, FIB, GAB2, LAMP3, ST3GAL1 and ST3GAL5 exhibit distinct expression profiles, with tumour tissues showing markedly different expression distributions compared to normal controls." (PMID 41362116, 2025). "We established a 7-plex mIF panel to detect lymphoid aggregates and TLS using markers against T cells (CD3), B cells (CD20), mature dendritic cells (Lamp3), macrophages (CD163), as well as endothelial cells (vWF) and tumor cells (pan-cytokeratin or MelA)." (PMID 40319321, 2025). "The role of LAMP3 in PCD and mitochondrial function is multifaceted, involving various aspects such as apoptosis, autophagy, and tumor immunity." (PMID 40297850, 2025). "For chemokine communications, the DC_LAMP3 subset expressed CCL22 and CCL17, which can bind to CCR4 to recruit Tregs into the tumor microenvironment." (PMID 38274387, 2024).
tumor (continued). "The CSF tumor microenvironment of the CUP-LM case showed CD8+ T cells in a dysfunctional state, an increased proportion of regulatory T cells (Treg) and LAMP3-positive dendritic cells, which helped shape an immunosuppressive landscape." (PMID 38274387, 2024). "To analyze the characteristics of the TIME in different tumor regions, we first detected the expression of immune markers including CD4+, CD8+, Foxp3+, CD20+, CD68+, LAMP3+, PD-1+ TILs, and PD-L1 in different tumor regions using IHC." (PMID 38254190, 2024). "We identified a mature DC cell, LAMP3 +DC, in CRC, which is believed to play a role in tumor cell migration in a variety of cancers." (PMID 37675100, 2023). "XCR1+ cDC1s play a key role in cross-presenting tumor antigens on MHC I to activate antitumoral cytotoxic T cells, and mature LAMP3-high DCs in our dataset had the highest expression of CD80/CD86 costimulatory signals needed to fully activate T cell responses." (PMID 37433281, 2023). "Performing flow cytometry on seven additional samples from patients with HPSCC verified that LAMP3+ DCs were present in the tumor and expressed higher PD-L1, CD83, and CCL19 levels than LAMP3– DCs." (PMID 37853464, 2023). "The analysis of mregDCs should be integrated in further studies of tumor-infiltrating DC subsets by using markers such as CCR7, LAMP3 and CD11c to distinguish them from other DC subsets." (PMID 37190135, 2023). "Cluster #4 presented with the most abundant expression of maturation markers including LAMP3, CD80, CD40, the migration marker CCR7, and overexpressed the tumor Secretory cDC2 signature, thus #4 was labeled mmDC." (PMID 35418195, 2022). "In high density of LAMP3-DC-mature-type TLS, CXCL9, 10 and 11 are involved in the migration of Th1 cells by binding to the CXCR3 receptor on tumor-infiltrating T cells." (PMID 36704336, 2022). "In contrast, LAMP3+ DCs can migrate from HCC tumors to lymph nodes and prime T cell migration to the tumor site." (PMID 35504878, 2022). "Thus, therapeutic targeting of LAMP3+ DCs might be only feasible in the early stage of NPC development so that effector lymphocytes can more effectively recognize the tumor antigens subsequently induce tumor depletion." (PMID 34568077, 2021). "For example, a low level of CCL21 expressed in LAMP3+ DCs hinders CCR7+ cells, which facilitates tumor growth and indicates an unfavorable prognosis for HCC patients." (PMID 33225985, 2020). "Mechanistically, it has been shown that tumor hypoxia induces unfolded protein response (UPR) pathway, which in turn induces LAMP3 via the PKR-like ER kinase (PERK)/activating transcription factor 4 (ATF4)-arm of the UPR." (PMID 25362357, 2014). "We observed a significant negative correlation between CD11c+ LAMP3+ IRF8+ DCs and TLS density, reinforcing the notion that LAMP3+ DCs contribute to TLS suppression and exert immunosuppressive effects within the tumor microenvironment, with IRF8 playing a key regulatory role in this process." (PMID 41190765, 2026). "We discovered that chemotherapy reshaped the tumor immune microenvironment, evident through the reduction in human leukocyte antigen (HLA) diversity and the increase in PDCD1/CD274 in CD8_ANXA1, LAMP3+ dendritic cell (DC_LAMP3), and EREG+ monocytes (mono_EREG)." (PMID 40725006, 2025). "Patients with tumours with high LAMP3 expression showed a poor prognosis, such as KIRC and KIRP, while patients with tumours with high LAMP3 expression showed a good prognosis such as BRCA and OV for the univariate Cox regression analysis, and survival analysis in online Kaplan–Meier and GEPIA." (PMID 38146591, 2024).
tumor (continued). "By employing single-cell analysis, we identified immunosuppressive LAMP3+ cDCs, likely promoting TREG migration into tumor tissues through the CCL17-CCR4 axis, in addition to increased CD163-positive macrophages previously associated with adverse TFHL prognoses." (PMID 38012392, 2024). "Finally, we experimentally verified the differential expression of LAMP3 in UCEC and normal tissues, its effect on tumor cell invasion and migration ability, and its effect on the expression of the MX2 and STAT1." (PMID 38217544, 2024). "Although LAMP3 is not ubiquitously expressed and its function in some tumours has been reported, the correlation between LAMP3 and pan‐cancer remains to be systematically studied." (PMID 38146591, 2024). "In addition, we conducted a Spearman correlation analysis to investigate the relationship between the expression levels of LAMP3, GZMB, and CXCL13 proteins and the cellular composition of the tumor microenvironment." (PMID 37512096, 2023). "LAMP3+DC highly expresses chemokine CCL19 and its receptor CCR7, which may recruit other immune cells to migrate to tumor tissues through the CCL19-CCR7 axis." (PMID 37675100, 2023). "In three independent cohorts of OC patients without neoadjuvant chemotherapy, it was shown that tumor-infiltrating mature migDCs (LAMP3-DCs) served as a favorable prognostic marker and were key in eliciting anti-tumor CD8+ T-cell responses." (PMID 36011029, 2022). "Mature LAMP3+ DCs were transformed from CD1C+ DC and CLEC9A+ DC sub‐clusters when exposure to tumour alloantigens, which may improve T cell cytotoxicity activities on tumour cells under anti‐PD‐L1 treatments." (PMID 36305631, 2022). "Our study demonstrated a remarkable increase of intratumoral LAMP3+ DCs aggregation in tumor lesions in neoadjuvant MPR tumor lesions, suggesting LAMP3+ DCs may contribute to the anti-tumor immune response of neoadjuvant chemoimmunotherapy." (PMID 35831283, 2022). "Interestingly, though LAMP3 expressed well in most of the ESCC tumor cells, only a small portion of CIC structures was positive in LAMP3, probably suggesting a low level of lysosomal activity in these CIC structures." (PMID 34178655, 2021). "Specially, tumor-infiltrating DC2 cells have been proven to be highly heterogeneous populations and deviated substantially from the other homogeneous cell types including DC1, LAMP3+ DC, and pDC." (PMID 32572028, 2020). "However, using such as dataset, we could show that TYK2 is prominently expressed in a conventional dendritic cell population positive for LAMP3 and CCR7, the chemokine receptor for homing to tumor-draining lymph nodes." (PMID 40991399, 2026). "Diverse components of the interferon-enriched community including LAMP3+ DC, CCL19+ fibroblast, CXCL9+ macrophage, and mesenchymal-derived interferon states confer favorable responses to immunotherapy and form different ecosystems between tumor, adjacent normal, and healthy normal tissues." (PMID 38744958, 2024). "However, there was no statistical significance between LAMP3 expression and age, gender, tobacco usage, alcohol consumption, tumor site, lymphovascular invasion, perineural invasion, and pattern of invasion." (PMID 39429383, 2024). "The mRNA expression of LAMP3 in other tumours could not be explored because of the absence of adequate paired samples." (PMID 38146591, 2024). "In our study, we demonstrated that NDV infection causes post-transcriptional degradation of both LAMP1 and LAMP2 proteins in various tumor and avian cells, while it does not significantly affect the expression of other lysosomal membrane proteins including LAMP3, LIMP II, and LAPTM5." (PMID 38354122, 2024). "In scRNAseq analyses of different cancer types from both mouse and human, specific tumor-infiltrating DC types or states were identified that are conserved between mouse and human, and on basis of their mRNA expression signatures termed DC330, LAMP3+ DC31 and mature regulatory (mreg)DC32." (PMID 36639382, 2023).